NLRP3 (NLR family pyrin domain containing 3)
Diseases named in the same sentence as NLRP3 in open-access papers (continued):
Sharing a sentence is not in itself a finding about the gene and the disease.
cardiac hypertrophy (continued). "The NLRP3 inflammasome, according to another report, could be upregulated and activated in the cardiac hypertrophy models, which aggravates cardiac fibrosis through activating the TGF-β/Smad pathway and promotes cardiac hypertrophy through activating the MAPK pathway." (PMID 35721118, 2022). "Therefore, MCC950 could significantly decrease susceptibility to VAs by reducing the myocardial inflammatory response, cardiac hypertrophy, and fibrosis by inhibiting NLRP3 inflammasome activation." (PMID 35287557, 2022). "However, the functions of the Nlrp3 inflammasome in mitochondria in Ang II-induced cardiac hypertrophy and cardiomyopathy remain unknown." (PMID 33628380, 2021). "However, the role of the Nlrp3 inflammasome in regulating mitochondrial dysfunction in Ang II-induced cardiac hypertrophy and cardiomyopathy remains unknown." (PMID 33628380, 2021). "It promotes the assembly and activation of NLRP3 complexes by activating the mitogen-activated protein kinase (MAPK)/NF-κB signaling pathway, thereby exacerbating TAC-induced pathological cardiac hypertrophy and dysfunction." (PMID 39925805, 2025). "In this study, we established a mouse model of myocardial hypertrophy via TAC and investigated the pathological role of NLRP3 inflammasome-mediated cell pyroptosis, as well as the potential therapeutic effect of MYOF." (PMID 39553724, 2024). "Increasing evidence suggests that NLRP3 (NOD-like receptor protein 3) and the pyroptosis cascade play critical roles in the development of cardiac hypertrophy and inflammation." (PMID 39553724, 2024). "Specifically, SIRT1 activationfinally alleviates cardiac hypertrophy by inhibiting the ROS-induced TGF1/Sma and mad homolog 3 (Smad3)signaling pathway and inhibiting NLRP3 inflammasome activation." (PMID 39484135, 2024). "Cardiac hypertrophy was induced in mice through a transverse aortic constriction (TAC) and this led to a significant increase in NLRP3 inflammasome components (NLRP3, ASC, and IL-1β)." (PMID 37336361, 2023). "Deletion of TRPV4 attenuated transverse aortic constriction (TAC)-induced cardiac hypertrophy, cardiac dysfunction, fibrosis, inflammation, and the activation of NFκB - NOD - like receptor pyrin domain-containing protein 3 (NLRP3) in mice." (PMID 35731090, 2022). "Cardiac hypertrophy significantly increased the percentage of apoptotic cells and upregulated IL-1β, cleaved caspase-1, and GSDMD-N that lie downstream of the NLRP3 inflammasome." (PMID 33723236, 2021). "Targeted inhibition of NLRP3 by CRID3 and gene silencing blocked caspase-1-dependent pyroptosis in cardiomyocytes and alleviated the signs of cardiac hypertrophy." (PMID 33723236, 2021). "Furthermore, given the known role of AT inflammation in instigating metabolic and cardiovascular complications, we also hypothesized that deletion of Nlrp3 would alleviate Western diet-induced glucose intolerance, arterial stiffening, and cardiac hypertrophy and fibrosis." (PMID 27583382, 2016). "Mechanistic analyses showed that THF mitigated myocardial hypertrophy by suppressing oxidative stress and inhibiting activation of the cGAS-STING pathway, thereby preventing downstream NLRP3 inflammasome-mediated pyroptosis and inflammatory cytokine production." (PMID 41798912, 2026). "It has been proved that NF- κB may be the upstream signal of the NLRP3 inflammasome, and MYOF may alleviate myocardial hypertrophy by inhibiting the NF- κB signaling pathway." (PMID 39553724, 2024). "Pharmacological depletion of extracellular ATP or genetic disruption of the P2X7 receptor suppressed myocardial NLRP3 inflammasome activity during pressure overload, underscoring the pivotal role of the NLRP3/ATP/P2X7 axis in cardiac inflammation and hypertrophy." (PMID 39594530, 2024). "However, the reversed effect of semaglutide on cardiac hypertrophy was abolished by HCQ, which restored the activation of NLRP3 inflammasome suppressed by improved mitophagy." (PMID 38782946, 2024).
cardiac hypertrophy (continued). "In addition to genetic disruption of NLRP3, pharmacological intervention inhibiting NLRP3 attenuated TAC-induced cardiac hypertrophy in mice." (PMID 37336361, 2023). "For instance, mice lacking NLRP3 were protected from developing cardiac hypertrophy induced by HS diet." (PMID 36364920, 2022). "Ang II, a powerful effector peptide of the RAAS and a hypertrophic agent, can induce cardiac hypertrophy and maladaptive cardiac remodeling by activating different signaling pathways, such as AKT/ERK, TGF-β/SMAD/collagen I/collagen III, NF-κB/NLRP3, NADPH kinases (NOX2 and NOX4)." (PMID 36386139, 2022). "In this context, a recent study demonstrated that NR administration favorably influenced cardiac hypertrophy and dysfunction induced by transverse aortic constriction (TAC) surgery in a mouse model by directly inhibiting myocardial NLRP3 inflammasome activation." (PMID 34943043, 2021). "The ablation of the NLRP3 inflammasome reduced cardiac hypertrophy, as there were no changes in Feret’s diameter with age and less significant increase in CSA and decline in mitochondria number." (PMID 33260800, 2020). "Mechanistically, GRK2 promotes the activation of the NLRP3 inflammasome and induces oxidative stress (OS) by downregulating the expression of nuclear factor erythroid-2-related factor 2 (Nrf2), thereby exacerbating isoproterenol (ISO)-induced pathological cardiac hypertrophy." (PMID 39925805, 2025). "Mice transverse aortic constriction (TAC)-induced cardiac hypertrophy model reported irisin treatment attenuates pressure overload-induced cardiac hypertrophy and fibrosis mainly through regulating AMPK-mTOR signaling or inhibiting NOD-like receptor protein 3 (NLRP3) -mediated pyroptosis activation." (PMID 35845994, 2022). "Collectively, these findings suggest that presence of the Nlrp3 gene is not required for Western diet-induced AT inflammation and glucose intolerance; yet, Nlrp3 appears to play a role in regulating arterial stiffening, cardiac hypertrophy and fibrosis." (PMID 27583382, 2016). "Moreover, we found that the expression of Il1b and Nlrp3 (which encode the cytokine IL-1β and the pyrin-like protein NLR family pyrin domain containing 3, respectively) were significantly upregulated in TAC-induced cardiac hypertrophy in Acsl4 F/F mice, but not in Acsl4 KO mice." (PMID 39327446, 2024).
gastric cancer (69 papers, 2013 to 2025). A primary or metastatic malignant neoplasm involving the stomach. "H. pylori infection has been associated with enhanced ROS production and NLRP3 expression in gastric cancer, triggering alterations in the M1 and M2 macrophage polarization." (PMID 39769450, 2024). "We investigated that PLCG1, CASP5, CASP8 and NLRP3 displayed the highest mutation frequencies in gastric cancer specimens." (PMID 37595258, 2023). "Association between NLRP1/NLRP3 expression level and clinicopathological characteristics in patients with gastric cancer by Kaplan-Meier plotter." (PMID 36541912, 2022). "As the best-characterized inflammasome, NLRP3 is known to be associated with the infiltration of various types of the immune cells and the induction of immune cell-mediated tumor suppression in gastric cancer, hepatic cancer, and lymphoma." (PMID 35123464, 2022). "MiR-22 inhibits gastric cancer cell growth through triggering a deficiency in endogenous S-adenosylmethionine, which can sustain NLRP3 expression and attenuate H. pylori-induced gastric cancer initiation." (PMID 35795038, 2022). "Additionally, the NLRP3 inflammasome has been linked to the regulation of IL-1β production, which is implicated in gastric cancer development." (PMID 39769450, 2024). "HP infection is considered the strongest single risk factor for gastric cancer and NLRP3 may be involved via the production of IL-1β." (PMID 37081882, 2023). "As reported, the activation of the NLRP3 inflammasome and production of large amounts of the pro-inflammatory factor IL-1β are crucial factors for the occurrence and progression of Hp-associated gastritis and gastric cancer." (PMID 36597090, 2023). "Additionally, those with NLRP3 polymorphisms (rs10754558 and rs4612666) are more susceptible to gastric cancer when infected with Helicobacter pylori." (PMID 32733479, 2020). "Beyond its effect on intestinal inflammation, the NLRP3 inflammasome is also involved in Helicobacter pylori infection-induced chronic gastric inflammation, which is the main cause of peptic ulcer disease and gastric cancer." (PMID 30823406, 2019). "BA exhibits the capability to induce pyroptosis in gastric cancer cells, primarily through the activation of NLRP3 inflammasomes." (PMID 38169542, 2024). "circCACNA2D1 expression is downregulated in gastric cancer; it sponges miR-223-3p, and miR-223-3p targets NLRP3." (PMID 39584140, 2024). "While recent studies have highlighted the crucial role of NLRP3-related pyroptosis in cancer therapy, the mechanistic intricacies surrounding pyroptosis in gastric cancer remain largely unexplored." (PMID 38169542, 2024). "Silencing NLRP3 has been demonstrated to reduce the effects of CagA on gastric cancer-cell migration and invasion, suggesting a potential role of NLRP3 in promoting the metastatic potential of gastric cancer." (PMID 39769450, 2024). "To elucidate the underlying mechanism of how ALKBH4 inhibits pyroptosis in gastric cancer cells, we evaluated the impact of ALKBH4 expression on key targets (GSDME, GSDMD, NLRP3, Caspase 1) of the pyroptosis pathway using qPCR and western blot experiments." (PMID 38902235, 2024). "Further, paclitaxel has been shown to prevent NLRP3-mediated migration and invasion of gastric cells, suggesting NLRP3’s involvement in the metastasis of gastric cancer." (PMID 39769450, 2024). "Collectively, these findings lend credence to the ability of BA to effectively activate NLRP3 inflammasomes, ultimately culminating in pyroptsis in gastric cancer cells." (PMID 38169542, 2024). "Silencing of NLRP3 reduces the effects of H. pylori infection on gastric cancer cell migration and invasion." (PMID 39145306, 2024). "To investigate the expression trends of NOTCH3 and immune infiltration-related factors in gastric cancer cells, we examined the protein expression of NLRP3, COX-2, and NF-κB p-p65 in HGC-27 cell line and normal gastric tissue." (PMID 38906903, 2024).
gastric cancer (continued). "Remarkably, Baicalin exhibits a dose-dependent reversal of the inhibitory influence exerted by MS on NLRP3 expression levels in gastric cancer cells." (PMID 38169542, 2024). "Therefore, exploring the mechanism of NLRP3 inflammasome activation in Hp-associated gastritis is of great significance for further understanding the pathogenesis of Hp-associated gastritis, the inflammation-carcinoma chain, and the prevention of gastric cancer." (PMID 36597090, 2023). "LncRNA ADAMTS9‐AS2 suppresses gastric cancer cells and raises cisplatin sensitivity by inhibiting miR‐223‐3p, which in turn stimulates NLRP3 expression and eventually enhances pyroptotic cell death." (PMID 37752941, 2023). "Low‐dose Diosbulbin‐B, a diterpene lactone isolated from Dioscorea bulbifera L,162 boosted the sensitivity of gastric cancer cells to cisplatin via inhibiting PD‐L1 and activating NLRP3‐mediated pyroptosis." (PMID 37752941, 2023). "The NLRP3 inflammasome regulates cyclin-D1, inducing IL-1β production to enhance differentiation of gastric cancer cells." (PMID 37081882, 2023). "Icariin, the primary active ingredient of Epimedium, controlled the hsa_circ_0003159/miR‐223‐3p/NLRP3 axis to suppress gastric cancer and trigger pyroptosis." (PMID 37752941, 2023). "Increasing DDP-sensitivity in gastric cancer by inducing pyroptosis via regulating the PD-L1/NLRP3 pathway." (PMID 38239395, 2023). "The high expression of NLRP3 in gastric cancer promotes the activation of NLRP3 inflammasome and the secretion of interleukin-1β (IL-1β) in macrophages." (PMID 36541912, 2022). "lncRNA ADAMTS9-AS2 acted as a tumor suppressor in gastric cancer (GC) cells by activating NLRP3-mediated pyroptotic cell death through sponging miR-223-3p." (PMID 35132346, 2022). "NLRP3 inflammosomes enhance the differentiation of gastric cancer cells by participating in cyclin-D1 and inducing IL-1β production." (PMID 35153782, 2022). "LncRNA ADAMTS9-AS2 served as a tumor suppressor and improved cisplatin sensitivity in gastric cancer cells through activating NLRP3-mediated pyroptotic cell death by sponging miR-223-3p." (PMID 35712671, 2022). "miR-330 was involved in the regulatory mechanism of NLRP3 inflammasome, and can inhibit the development of liver cancer, gastric cancer, and osteosarcoma." (PMID 36119061, 2022). "For example, low-dose diosbulbin-B (DB) exhibited antitumor effects in gastric cancer by the activation of NLRP3-mediated pyroptotic cell death to enhance the cytotoxic effect of cisplatin-based chemotherapy." (PMID 35392086, 2022). "UALCAN analysis of TCGA data showed that NLRP1/NLRP3 expression level in primary gastric cancer was significantly higher than normal tissues (**p < 0.01, ***p < 0.001)." (PMID 36541912, 2022). "Overexpressed LncRNA ADAMTS9-AS2 inhibits gastric cancer (GC) progression by regulating miR-223-3p/NLRP3 axis-mediated pyroptosis." (PMID 34805183, 2021). "And a recent study demonstrated that inhibiting NLRP3 inflammasome and limiting IL-1β secretion were the main mechanisms of miR-22-induced decreased gastric cancer cells proliferation." (PMID 34211462, 2021). "NLRP3 is markedly upregulated in gastric cancer, which promotes NLRP3 inflammasome activation and IL-1β secretion in macrophages." (PMID 32796686, 2020). "NLRP3-mediated IL-1β production activates NF-κB and initiates JNK signaling to cause proliferation in gastric cancer and CRC." (PMID 33613533, 2020). "This study indicates a proliferative effect in epithelia and a carcinogenic role for upregulated epithelial NLRP3 in the development of mouse and humans gastric cancer." (PMID 32778128, 2020). "The H. pylori infection markedly suppresses miR-22 expression, an event that prevents miR-22 from suppressing NLRP3 expression, attenuating NLRP3-driven cell proliferation and preventing gastric cancer carcinogenesis." (PMID 32796686, 2020).
gastric cancer (continued). "NLRP3 enhances IL-1β, subsequently activating NF-κB, and initiates JNK signaling to cause proliferation and invasion in gastric cancer." (PMID 33613533, 2020). "H. pylori infection enhances NLRP3 expression in gastric cancer and triggers the uncontrolled proliferation of epithelial cells." (PMID 33613533, 2020). "Increased activation of the NLRP3 inflammasome promotes migration and invasion activities in gastric cancer cells." (PMID 33613533, 2020). "The cascade of downstream pathways via activation of the NLRP3-mediated IL-1β axis has been found to activate NF-κB that initiates JNK signaling causing proliferation and invasion in gastric cancer." (PMID 33613533, 2020). "The NLRP3 inflammasome enhances cell differentiation in gastric cancer by engaging cyclin-D1 as well as inducing IL-1β production." (PMID 30447690, 2018). "Next, we treated these gastric cancer cells with the culture supernatants from M.hy challenged THP-1 derived macrophages or macrophages with silencing of NLRP3, ASC and caspase-1 for migration and invasion assay." (PMID 24223129, 2013). "In this study, we found that M.hy triggered IL-1β secretion in a NLRP3 inflammasome-dependent manner, and the resulting IL-1β induced migration and invasion of gastric cancer cells." (PMID 24223129, 2013). "Our results showed that M.hy activated the NLRP3 inflammasome in vitro and in vivo, and the promotion of gastric cancer cell migration and invasion by M.hy was dependent on NLRP3 inflammasome activation." (PMID 24223129, 2013). "In addition, in gastric cancer (GC) through regulation of miR‐223‐3p/NLRP3 axis to induction of NLRP3 inflammasome activation and upregulation of IL‐1β secretion which drives epithelial cell proliferation and tumorigenesis." (PMID 40671401, 2025). "Furthermore, overexpressed long non-coding RNA ADAMTS9-AS2 has been shown to inhibit gastric cancer development by regulating the miR-223-3p/NLRP3 axis, suggesting a potential tumor-suppressive role for NLRP3 in gastric cancer." (PMID 39769450, 2024). "Additionally, studies have shown that CagA protein activates the NLRP3 inflammasome, promoting migration and invasion of gastric cancer cells." (PMID 38916312, 2024). "Further, several studies have shown that NLRP3 is highly expressed in stomach adenocarcinoma, and could serve as a potential prognostic biomarker for gastric cancer." (PMID 39769450, 2024). "CagA, a Helicobacter pylori virulence factor, may trigger the migration and invasion of gastric cancer cells by activating the NLRP3 inflammasome." (PMID 37752941, 2023). "NLRP3 plays a key role in the development of gastric cancer." (PMID 35896522, 2022). "Notably, the overexpression of the lncRNA ADAMTS9-AS2 inhibits gastric cancer progression and promotes cisplatin chemosensitivity by regulating the miR-223-3p/NLRP3 axis-mediated pyroptosis process." (PMID 35392086, 2022). "Moreover, Mycoplasma hyorhinis, which was detected in 56% of gastric cancer, was also found to be able to active NLRP3 inflammasome and induce IL-1β secretion, thus promote gastric cancer cell migration and invasion." (PMID 36619871, 2022). "NLRP3 showed stronger correlations with immune infiltration and the prognosis of gastric cancer." (PMID 36541912, 2022). "In addition, NLRP3 can inhibit the antitumor immune response of gastric cancer by activating cell death." (PMID 35782053, 2022). "H. pylori infection weakens miR-22 expression and thus up-regulates NLRP3 inflammasome activation and release of oncogenic mature IL-1β, thereby triggering uncontrolled proliferation of epithelial cells and the occurrence of gastric cancer." (PMID 35795038, 2022). "Recent evidences suggested that activation of NLRP3 inflammasome by mycoplasma hyorhinis promotes gastric cancer migration and invasion, and this gastric tumor-promoting effect by NLRP3 may be due to the activating CCND1 transcription." (PMID 34211462, 2021).